MT-TE (mitochondrially encoded tRNA-Glu (GAA/G))
Synonyms: trnE; formerly MTTE
Gene: Mitochondrial transfer RNA gene on chromosome MT (14,674 to 14,742, reverse strand). Ensembl gene ENSG00000210194.
Gene-disease validity (ClinGen):
ClinGen rates the evidence that MT-TE causes each of these diseases.
mitochondrial disease (mitochondrial): Definitive.
Homologues: Orthologues: chimpanzee MT-TE (100% identical).
Diseases named in the same sentence as MT-TE in open-access papers:
MT-TE is named in the same sentence as 6 diseases in open-access papers, as found by Europe PMC text mining. Sharing a sentence is not in itself a finding about the gene and the disease. The quoted sentences say what the papers report.
Ataxia (1 paper, 2023). Ataxia refers to impaired coordination of voluntary muscle movement. "Mutations in the MT-TE gene have already been associated with the development of diabetes and myopathies, as well as early-onset cataracts, ataxia and progressive paraparesis, but there are no reports in the literature about the variant found in our study." (PMID 38062538, 2023).
Mitochondrial myopathy (1 paper, 2016).
MT-TE also shares sentences with these, for which no sentence is quoted: cataract (1 paper); diabetes (1); Leber hereditary optic neuropathy (1); myopathies (1).